SLC6A14 (solute carrier family 6 member 14)
Diseases named in the same sentence as SLC6A14 in open-access papers (continued):
Sharing a sentence is not in itself a finding about the gene and the disease.
cancer (continued). "Indeed, SLC6A14 expression and function have been mostly investigated in cancers so far." (PMID 35372502, 2022). "Therefore, the suppression of glutamine uptake via the downregulation of SLC6A14 expression may increase the efficacy of cancer chemotherapy." (PMID 35625849, 2022). "However, whether α-MT can be a candidate for novel approaches to CRC therapy requires further study on the role of SLC6A14 in a variety of cancers." (PMID 35907820, 2022). "In some pathophysiological conditions including certain cancer types (colorectal, cervical, estrogen receptor positive breast, pancreatic) the high demand for supply of amino acids to drive growth and proliferation is accomplished partly via increased expression of SLC6A14." (PMID 36291613, 2022). "Based on the role of SLC6A14 in cancer cell metabolism and growth, and the finding that Panc-1 is more malignant than AsPC-1, the data suggest that alloferon could be used as a chemo-adjuvant drug to regulate metastasis and the proliferation of more aggressive cancers." (PMID 35625849, 2022). "In support of the critical role of SLC6A14 in DEHP‐induced glutamine uptake and cancer stemness, DEHP‐promoted spheroid formation of MCF7 cells was significantly suppressed by silencing SLC6A14 expression with specific shRNA." (PMID 40959920, 2025). "It suggested that SLC6A14‐dependent glutamine uptake mediates DEHP‐elicited mitochondria fusion and respiration by suppressing MFF expression to promote cancer stemness." (PMID 40959920, 2025). "Beyond PDAC, clinical and preclinical studies in other cancers have demonstrated the efficacy of targeting SLC transporters such as SLC7A5 (LAT1), SLC16A1 (MCT1), and SLC6A14 in suppressing tumor growth and modulating therapeutic resistance." (PMID 40282424, 2025). "Cancer cells take up tryptophan via SLC7A5 and SLC6A14 and, once inside the cell, tryptophan gets degraded by indoleamine-2,3-dioxygenase-1 (IDO1)." (PMID 38339256, 2024). "They further characterize cytosolic SLC6A14 and mitochondrial SLC25A15 as mediators of adequate serine supply to sustain cancer cell proliferation." (PMID 38066114, 2023). "Using physiologically relevant conditions, we found that SLC6A14 is a plasma membrane serine transporter and SLC25A15 a mitochondrial serine transporter in cancer cells." (PMID 38066114, 2023). "These dual-targeting liposomes showed highest uptake efficiency in BxPC-3 and MCF-7 cancer cells, which highly express both LAT1 and SLC6A14." (PMID 36770817, 2023). "In contrast to SLC6A14 and SLC38A5, the other three transporters related to cancer are all amino acid exchangers, meaning that the influx of one amino acid substrate into cells is coupled to the efflux of another amino acid substrate out of the cells." (PMID 33806675, 2021). "SEC24C has previously been shown to be phosphorylated by protein kinase B/AKT, which is hyper-activated in cancer; therefore, we analyzed the influence of AKT on SLC6A14 trafficking to the cell surface." (PMID 34359969, 2021). "To date, four distinct amino acid transporters have received increasing attention for their role in the promotion of cancer: SLC1A5 (also known as ASCT2), SLC7A5 (also known as LAT1), SLC7A11 (also known as xc−), and SLC6A14 (also known as ATB0,+)." (PMID 33806675, 2021). "SLC6A14, an amino acid transporter B0,+ (ATB0,+) that is upregulated in many cancers, transports all but acidic amino acids." (PMID 34359969, 2021). "Since glutamine is a good substrate for SLC6A14 and SLC38A5, the Na+-coupled concentrative influx of these amino acids into cancer cells is likely to activate the heterodimeric amino acid transporter known as cystine/glutamate exchanger (SLC7A11/4F2hc)." (PMID 33806675, 2021). "As such, SLC6A14 and SLC38A5 drive cancer cell proliferation and tumor growth in specific types of solid tumors." (PMID 33806675, 2021).
cancer (continued). "Moreover, we performed pan-cancer assays and found that LAMC2, CTSE and SLC6A14 exhibited a dysregulated level in many types of tumors, highlighting their potential function in tumor progression." (PMID 38267509, 2024). "Recently, SLC6A14 and SLC38A5 have been shown to be upregulated in various cancers and mediate the influx of glutamine, serine, glycine and methionine into cancer cells and are suitable for the rapid proliferation of cancer cells." (PMID 38785550, 2024). "SLC6A14 was found in the tumour area with immune exclusion, associated to amino acid supplementation, promoted EMT‐induced metastasis in cancer." (PMID 39187937, 2024). "Since SLC6A14 can also transport L-carnitine, albeit with a lower affinity than OCTN2/SLC22A5, similar nanoparticles have been shown to bind to and utilize both transporters in various cancer cell lines." (PMID 36770817, 2023). "Cancer cells upregulate multiple amino acid transporters as a means to increase the influx of amino acids from circulation; this includes the transporters SLC7A5 (LAT1), SLC1A5 (ASCT2), SLC6A14 (ATB0,+), SLC7A11 (x-c), SLC38A5 (SNAT5) and SLC43A2." (PMID 36765717, 2023). "Therefore, SLC6A14 is a viable drug target for the treatment of PDAC and also for any other cancer that overexpresses this transporter." (PMID 35212370, 2022). "SLC6A14 (ATB0,+) that broadly accepts large neutral amino acids, as well as SLC38A2 (SNAT2), SLC38A3 (SNAT3) and SLC38A7 (SNAT7) that accept some large neutral amino acids such as His, Met and Leu are known to be upregulated in certain types of cancers." (PMID 36071551, 2022). "SLC6A14 and SLC38A5 are cell-surface proteins that support amino acid nutrition in cancer cells." (PMID 33806675, 2021). "SLC6A14 and SLC38A5 are the two transporters that are upregulated in a variety of cancers to mediate the influx of glutamine, serine, glycine, and methionine into cancer cells." (PMID 33806675, 2021). "SLC6A14 and SLC38A5 represent two such transporters with their unique amino acid substrate profiles and functional features that have been shown to be connected to cancer." (PMID 33806675, 2021). "SLC6A14 was recently identified as a novel druggable target in PDAC, suggesting the validity of our screening results, whereas the role of SLC41A1 has rarely been studied in cancer." (PMID 31076559, 2019). "Development of amino acid-based prodrugs that are recognized as substrates by SLC6A14 is an emerging strategy designed to exploit this vulnerability and target drugs to cancer cells with upregulated SLC6A14." (PMID 28350329, 2017). "CFTR, found in epithelial cells functions as a cAMP-activated ATP-gated anion channel and SLC6A14 functions as Na+ and Cl− dependent neutral and basic amino acid transporter, but their roles in cancer are not known." (PMID 25505737, 2014). "Interestingly, similar to SLC6A14, the expression of SLC38A5 is also under the control of the Wnt signaling pathway, thus suggesting a probable connection between this transporter and cancer." (PMID 33806675, 2021). "The most studied transporters for their role in cancer include SLC1A5 (alanine–serine–cysteine transporter 2 or ASCT2), SLC7A5 (system L amino acid transporter 1 or LAT1), SLC7A11 (system x−c transporter or xCT), and SLC6A14 (amino acid transporter B0,+ or ATB0,+)." (PMID 34704597, 2021). "Moreover, since the activity of SLC6A14 does not deprive cells of other amino acids, as in the case of exchangers, this regulation is important for cell growth, a process crucial for cancer cells in which AKT is hyper-activated." (PMID 34359969, 2021). "SLC6A14 has the highest affinity for the nonpolar amino acids isoleucine, leucine, methionine, valine and serine; however, glutamine and arginine are among its substrates, and it is worth mentioning that glutamine, arginine and leucine are especially important for the growth of cancer cells." (PMID 34359969, 2021).
tumor (47 papers, 2015 to 2026). "Strong association between SLC6A14 upregulation and tumour progression has been reported in colorectal cancer." (PMID 41302469, 2025). "To learn more about how SLC6A14 contributed to PC development, we conducted in vivo experiments and found that tumor weights in the SLC6A14-deficient group were significantly lower than those in the sh-control group." (PMID 38267509, 2024). "LC–MS-based metabolomics on tumor lysates demonstrated lower tumor serine and glycine levels upon deletion of SLC6A14/12A4 and SLC6A14/25A15 in HCT116 PHGDH-deficient xenografts, whereas serine and glycine levels in the circulating blood remained unaltered." (PMID 38066114, 2023). "Four genes were associated with the tumor stage, including solute carrier family 6 member 14 (SLC6A14), polypeptide N-acetylgalactosaminyltransferase 5 (GALNT5), tetraspanin 1 (TSPAN1), and islet amyloid polypeptide (IAPP)." (PMID 34591244, 2021). "Altogether, our data indicate that AMPK activation is a metabolic vulnerability in SLC6A14-deficient cells that can be exploited as a therapeutic approach to drive unbalanced metabolism in starved tumor cells." (PMID 33400734, 2020). "Interestingly, the only somatic nsSNV present in all tumor samples was a SLC6A14 p.R614H variant of unknown significance (VUS)." (PMID 41331048, 2025). "In addition to TRIM24::NTRK2 and CDKN2A/B HD, a SLC6A14 missense variant (p.R614H) of unknown significance (VUS) was present in all six tumor specimens." (PMID 41331048, 2025). "We speculate that apart from suppressing IDO1 expression and function, carbidopa serve to inhibit tryptophan entry into tumor cells and tumor-associated immune cells by blocking either the Tryptophan-selective transporter or other amino acid transporters such as SLC6A14 that transport Tryptophan." (PMID 35997090, 2022). "Then the CXCL5-CXCR2 and LGALS9-HAVCR2 were identified in the cell-cell communication between CXCL5+ SLC6A14+ tumor cells and MRC1+ macrophages." (PMID 39670859, 2025). "Given that CXCL8 enhances fibroblast activation via CXCR2 signaling, we propose that SLC6A14 regulates tumor–stroma interactions by sustaining CXCL8 secretion." (PMID 41444422, 2025). "Targeting SLC6A14 with α-methyl-tryptophan enhanced gemcitabine sensitivity, suppressed PD-L1 driven immune evasion and reduced tumor growth, metastasis and glutamine production in vivo." (PMID 41444422, 2025). "H&E staining revealed less aggressive tumor morphology in SLC6A14-depleted gemcitabine-resistant tumors." (PMID 41444422, 2025). "In estrogen receptor-positive breast cancer, SLC6A14 expression was approximately nine-fold higher than in normal tissue and supported tumour growth by supplying leucine and arginine." (PMID 41302469, 2025). "Inhibition of SLC6A14 reduces stemness, impairs tumor growth, and sensitizes tumors to chemotherapy." (PMID 40959920, 2025). "Inhibition of SLC6A14 repressed DEHP‐associated mitochondrial fusion and oxidative phosphorylation, CSC activity, and tumor progression." (PMID 40959920, 2025). "We believe this comprehensive approach will provide the necessary validation and insight into the interaction between MRC1+ TAMs and CXCL5+SLC6A14+ tumor cells." (PMID 39670859, 2025). "Levels of phosphorylated mTOR, NF-κB, PD-L1 and Ki-67 (a marker of tumor proliferation) were also reduced following SLC6A14 inhibition." (PMID 41444422, 2025). "In breast cancer, SLC6A14-mediated amino acid uptake activates mTORC1 signaling, which drives tumor progression and metastasis." (PMID 41444422, 2025). "Then, we developed a novel diagnostic model using LAMC2, SLC6A14 and CTSE, which showed a strong predictive ability in screening PC specimens from non-tumor specimens in several GEO datasets." (PMID 38267509, 2024).
tumor (continued). "Therefore, based on the findings of our study, immunosuppression brought on by an increased number of M0 macrophages cells in the primary tumor microenvironment may be the cause of a worse 5-year survival rate in patients with PC who have a high level of SLC6A14." (PMID 38267509, 2024). "Nevertheless, genes such as Nell2, Smarca1, Slc6a14 and Grhl3 which were highly downregulated by the combined treatment were reported to contribute to tumor progression." (PMID 39450263, 2024). "Collectively these results suggest that in serine synthesis-deficient tumors, targeting SLC6A14 together with an ion exchanger/facilitator (SLC12A4) or a mitochondrial serine transporter (SLC25A15) can decrease serine uptake, leading to reduced tumor growth." (PMID 38066114, 2023). "Among the top two DEGs SLC, SLC6A14 was upregulated in 6 tumor types, whereas SLC26A10 was downregulated in 5 tumors." (PMID 37397501, 2023). "Nevertheless, in established serine synthesis-deficient tumor xenografts, acute silencing of SLC6A14/SLC12A4 and to a lesser degree SLC6A14/SLC25A15 reduced tumor growth and serine levels, despite a large proportion of DOX escapers." (PMID 38066114, 2023). "Despite a mixed cell population in terms of DOX responsiveness (Cas9 was predicted to be induced in ~25% of the population ), deletion of SLC6A14/12A4, and to a lesser degree SLC6A14/25A15, slowed tumor growth and conferred a survival benefit." (PMID 38066114, 2023). "Its concentrative nature and the broad spectrum of amino acids, including the essential ones, it transports make SLC6A14 the ideal transporter for tumour growth and development." (PMID 36286592, 2022). "Pharmacological blockade and gene silence of SLC6A14 enormously wrecked the migrated and invasive ability of GC cells and lessened GC metastasis in tumor-bearing mice." (PMID 35865664, 2022). "Mechanistically, SLC6A14 was demonstrated to regulate the expression and phosphorylation of Akt-mTOR, which mediates the promoting tumor growth function of SLC6A14." (PMID 35907820, 2022). "We found the effects of SLC6A14 on tumor cell growth in vitro and tumorigenesis in vivo, and confirmed that Akt-mTOR signaling was activated in SLC6A14-mediated CRC progression." (PMID 35907820, 2022). "We have demonstrated that the expression levels of SLC6A14 were closely related to the tumor cells differentiation: the higher the expression of SLC6A14 was, the poorer the differentiation of the tumor was." (PMID 35907820, 2022). "Taken these data together, it suggested that SLC6A14 regulated the activity of Akt-mTOR signaling molecules, which is a key pathway in the control of tumor cell proliferation and mobility." (PMID 35907820, 2022). "SLC6A14 knockout mice showed a low tumor incidence with normal fertility and mammary gland development." (PMID 35907820, 2022). "SLC6A14 was found to be highly expressed in colorectal tissues, due to the increased demand of tumor cells for leucine and arginine." (PMID 34095122, 2021). "This increase in mRNA was further confirmed at protein level and more than 75% of tumor cells were stained with anti-SLC6A14 antibody." (PMID 33195271, 2020). "Methionine deprivation, which can be achieved via modulation of dietary methionine intake in tumor cells, in turn leads to a heightened activation of the AMP-activated kinase (AMPK) in SLC6A14-deficient cells." (PMID 33400734, 2020). "In one study, when the MCF-7 cell line was co-cultured with fibroblasts, the expression of GLS, GDH, and SLC6A14 (glutamine importer) in tumor cells increased and glutamine neosynthesis decreased compared to when the cell line was cultured alone." (PMID 27447554, 2016). "A total of 174 tumor cores from 94 patients were evaluated for SLC6A14 staining intensity, percentage of tumor cells stained for SLC6A14, and subcellular localization of SLC6A14 staining." (PMID 26106611, 2015).
tumor (continued). "We also examined the relationship between SLC6A14 staining intensity and patient demographics, including survival after resection, tumor stage, and tumor grade." (PMID 26106611, 2015). "As we found in the bulk tumor samples, SLC6A14 was highly overexpressed in this patient group after LCM." (PMID 26106611, 2015). "The 154 cores with weak to strong staining were then scored for the percentage of tumor cells within the core that were stained for SLC6A14." (PMID 26106611, 2015). "In addition, direct validation through in vitro or in vivo experiments is essential to establish the interaction between MRC1+ TAMs and CXCL5+SLC6A14+ tumor cells." (PMID 39670859, 2025). "Co-injection with CAFs further increased tumor growth, which was reduced by SLC6A14 inhibition." (PMID 41444422, 2025). "Given the link between SLC6A14 and tumor progression, its role in metastasis was examined." (PMID 41444422, 2025). "SLC6A14 has received much attention for its role as a tumor promoter (Nałęcz, 2020)." (PMID 39902076, 2024). "Hence, SLC6A14 emerges as a promising target for tumor therapy, with its potential extending to enabling the selective delivery of anticancer drugs to tumor cells." (PMID 38218942, 2024). "Our above results suggested SLC6A14 as a tumor promotor in PC progression." (PMID 38267509, 2024). "Previously, several studies have reported the function of LAMC2 and SLC6A14 in tumor progression." (PMID 38267509, 2024). "Due to the role of SLC6A14 in tumor progression, its inhibition may aid tumor regression and treatment." (PMID 38434708, 2024). "Moreover, in xenograft and syngeneic mouse tumor models, silencing of SLC6A14 or suppressing its action by α-MT reduces the size of tumor via targeting of β-catenin." (PMID 37373349, 2023). "Both of the mRNA and protein levels of SLC6A14 were upregulated in CRC tissues, and the protein levels of SLC6A14 were closely related to the tumor cells differentiation: the higher the expression of SLC6A14 was, the poorer the differentiation of the tumor cells was." (PMID 35907820, 2022). "Furthermore, we identified α-MT as an effective inhibitor targeting SLC6A14 to suppress tumor growth in CRC." (PMID 35907820, 2022). "SLC6A14, the newest member belonging to SLCs, can mediate the uniport of almost all the essential amino acids into cells and is ideal to meet the inordinate demands of tumor cells for amino acids." (PMID 35865664, 2022). "In conclusion, our experiments indicated that SLC6A14 was upregulated and could activate the Akt-mTOR signaling pathway, thereby promoting the tumor progression of CRC." (PMID 35907820, 2022). "Therefore, it seems that the upregulation of SLC6A14 with its tumor-promoting capability represents at least one of the molecular mechanisms by which estrogen signaling and Wnt signaling drive carcinogenesis and tumor growth." (PMID 33806675, 2021). "In particular, we focused on the evaluation of SLC6A14 function under conditions of metabolic stress which are generally experienced by tumor cells either because of intrinsic characteristics of the tumor microenvironment or as a result of drugs targeting metabolic pathways." (PMID 33400734, 2020). "However, very little is known about SLC6A14 expression, subcellular localization, and transporter function at the protein level in any of these tumor types." (PMID 26106611, 2015). "Therefore, targeting SLC6A14 or glutamine metabolism may offer a promising therapeutic strategy to overcome gemcitabine resistance by disrupting tumor–stroma interactions and restoring immune surveillance." (PMID 41444422, 2025). "Moreover, SLC6A14, SLC34A2, and SLC1A2 were linked to tumor immune responsiveness." (PMID 37397501, 2023). "Notably, SLC6A14 expression was positively correlated with the depth of tumor invasion (∗P = 0.023), the disposition to distant metastasis (∗∗P = 0.009), venous invasion (∗P = 0.033), lymph node metastasis (∗P = 0.035), and lymphatic invasion (∗∗P = 0.021) in GC patients." (PMID 35865664, 2022).